STAT3 (signal transducer and activator of transcription 3)
Diseases named in the same sentence as STAT3 in open-access papers (continued):
Sharing a sentence is not in itself a finding about the gene and the disease.
glioma (continued). "The oncogenic role of STAT3 in gliomas is consistent with the observation that STAT3 activation is rarely detected in normal brain tissues." (PMID 24743777, 2014). "Phosphorylated STAT3 (p-STAT3), which is overexpressed in most gliomas translocates into the nucleus and induces a variety of transcriptional factors, including IL-10." (PMID 25505736, 2014). "Activated TLR9 also promoted growth of glioma stem-like cells through the activation of STAT3 signaling in vitro, which is a pathway participating in numerous tumor promoting activities." (PMID 25411122, 2014). "The study also revealed that the glioma cells induced microglia to secrete the anti-inflammatory cytokine IL-10 and to up-regulate STAT3 signaling activity, two activities that are tumor promoting." (PMID 25411122, 2014). "STAT3 knockdown with interfering RNA, delivered by a lentivirus vector, resulted in down-regulation of cyclin D1 and inhibition of glioma cell proliferation." (PMID 24518612, 2014). "WP1066 was first introduced in 200720, 21 as a JAK kinase inhibitor in acute myelogenous leukemia and glioma, and now it is used as a STAT3 phosphorylation (Tyr 705 residue) blocker." (PMID 25514838, 2014). "A number of approaches have been developed to target STAT3 or its downstream effects and thereby inhibit glioma growth." (PMID 24518612, 2014). "The mechanism for this is likely due to the dual inhibition of phosphorylated forms of JAK2 and STAT3 thereby reducing STAT3 transcriptional activity, as has been shown for several cancer cell lines including glioma, myeloid leukemia, and melanoma." (PMID 24804649, 2014). "WP1193 is a small molecule inhibitor of JAK2/STAT3, which promotes in vivo glioma inhibition in a dose-dependent manner and is partially associated with G1 arrest in GSCs." (PMID 24518612, 2014). "TNF-α has been recently demonstrated to induce IL-6 expression via STAT3 pathway in C6 glioma cells." (PMID 25275372, 2014). "We have demonstrated that CX-4945 decreases NF-κB, PI3K/Akt and JAK/STAT3 signaling in glioma and increases survival time in an intracranial murine model of glioma." (PMID 25153725, 2014). "Resveratrol, a grape polyphenol, has been shown to enhance glioma radiosensitivity by inhibiting STAT3 signaling, rendering future promise for more effective radiotherapy." (PMID 24518612, 2014). "miR-155 targets suppressor of cytokine signaling (SOCS) proteins potentially leading to overactive Stat3, a transcription factor important in glioma progression." (PMID 25054228, 2014). "miRNA expression can be induced by hypoxia and hypoxia contributes to the immune escape of gliomas in a signal transducer and activator of transcription 3 (STAT3)-dependent manner via induction of regulatory T cells." (PMID 25277195, 2014). "RUNX1 is a major regulator of the glioma mesenchymal subtype, and was found to interact with STAT3 in the miRNA-mediated RNA-RNA interaction network; it is therefore not unexpected that RUNX1 expression was downregulated by blocking the activity of STAT3." (PMID 25007077, 2014). "C/EBP-β (CEBPB) and STAT3 have previously been shown to synergistically induce mesenchymal transformation of glioma cells." (PMID 23408876, 2013). "In fact, human U251 glioma cells engineered to either over-express STAT3 or with genetic down-regulation of STAT3 supported oHSV replication to a significantly higher or lesser degree, respectively, when compared to controls." (PMID 23936533, 2013). "More recently, it has been demonstrated that STAT3 binds to the transactivation domain (TAD) of NF-κB p65 to cooperatively induce gene expression in glioma cells following radiation." (PMID 24244348, 2013). "EGFR amplification is seen in approximately 50% of GBM, and in approximately 50% of those tumors the glioma cells express EGFRvIII, a mutant receptor that persistently activates downstream immunosuppressive pathways including those involving STAT3." (PMID 23737783, 2013).
glioma (continued). "In agreement with published findings, interleukin (IL)-6 treatment of glioma cells increased STAT3 activity." (PMID 23936533, 2013). "In contrast, mice receiving AZD1480 alone exhibited the smallest tumor volumes, consistent with our previous findings that STAT3 inhibition reduced glioma tumor volume." (PMID 24244348, 2013). "To evaluate the effect of pharmacological inhibition of NF-κB and/or STAT3 in vivo, we proceeded to the orthotopic intracranial xenograft model of glioma." (PMID 24244348, 2013). "It corresponds to our recent studies that demonstrate unaffected survival of C6 glioma cells with siRNA mediated Stat3 knockdown." (PMID 24170218, 2013). "In this report, we show that genetic or pharmacologic activation of STAT3 in glioma cells enhanced oHSV replication while knockdown or pharmacologic inhibition of STAT3 reduced oHSV replication." (PMID 23936533, 2013). "STAT3 activation in glioma TAMs is induced by many mediators known to compose the local tumor microenvironment such as IL-10, IL-6, EGF, and FGF." (PMID 23737783, 2013). "Next, we compared the cytotoxicity of oHSV against STAT3 over-expressing glioma cells or glioma cells with STAT3 knock-down by shSTAT3." (PMID 23936533, 2013). "Han's study demonstrated that β-catenin pathway regulates miR-21 expression via STAT3 playing a role in human glioma cell." (PMID 24565222, 2013). "In fact, human glioma cells that constitutively express STAT3 significantly enhanced replication of the virus by factors of 10-15, while decreasing STAT3 by shRNA led to the opposite effect." (PMID 23936533, 2013). "In this context, recent evidence has emerged to show that activation of the STAT3 pathway represents a central hub in glioma progression and maintenance." (PMID 23936533, 2013). "Our group showed that conditioned medium from glioma cells increased STAT3 activity in microglia cells, resulting in overexpression of IL-6 and IL-10 and downregulation of IL-1β." (PMID 23864876, 2013). "In this report, we show for the first time that STAT3 activation leads to enhanced replication of oHSV in glioma cells." (PMID 23936533, 2013). "Although we have not formally proven that the STAT3 mechanism of oHSV-mediated enhancement of viral replication in glioma cells depended on STAT3-mediated reduction of ISG, this remains a very likely mechanism." (PMID 23936533, 2013). "STAT3 activation usually relies on ligand-receptor interactions, but STAT3 becomes persistently activated in most human malignancies, including gliomas." (PMID 23013619, 2012). "WP1066 selectively inhibits the STAT3 pathway and reduces STAT3-driven expression of Bcl-2, Bcl-xL, and Mcl-1, triggering Bax activation and resulting in extended survival of xenogeneic glioma mouse models." (PMID 22431925, 2012). "Because surgery in close proximity to a recent dose of bevacizumab is contraindicated, we can't exclude that during the ensuing interval that there are changes in the human glioma p-STAT3 level." (PMID 23013619, 2012). "Our results are also consistent with the previously demonstrated prognostic influence of p-STAT3 on survival in patients with other types of malignancies, such as glioma." (PMID 22488042, 2012). "Cediranib-treated NSC11 glioma cells also showed a significant elevation of p-STAT3 expression, with a mean percentage of p-STAT3-expressing cells of 16.2 + 4.8% (median 16.5; range 10.0 – 22.4; n=7; P=0.05)." (PMID 23013619, 2012). "Taking our findings into account, it is most likely that midazolam inhibits IL-1β-induced IL-6 release through the JAK/STAT3 pathway suppression in C6 glioma cells." (PMID 21682888, 2011). "We previously reported that IL-1β induces activation of IκB, p38 MAP kinase, SAPK/JNK, Erk 1/2 and STAT3 in C6 glioma cells." (PMID 21682888, 2011). "In conclusion, our findings strongly suggest that midazolam inhibits IL-1β-induced IL-6 release in rat C6 glioma cells via suppression of STAT3 activation." (PMID 21682888, 2011).
glioma (continued). "In summary, both of these recent reports indicate that HCMV US28 can drive oncogenic signaling through two key pathways that are involved in cancer stem cell maintenance and glioma proliferation and invasion--STAT3 and GSK3-β/β-catenin." (PMID 22030012, 2011). "Recently, STAT3 was reported to be over expressed and active in gliomas, and its deletion induces spontaneous apoptosis in glioma cell lines." (PMID 21595984, 2011). "Gliomas seem to depend on activated STAT3: inhibition of STAT3 is known to suppress proliferation, and STAT3 knockdown reportedly induces apoptosis in glioma cells." (PMID 20840775, 2010). "STAT3 is constitutively activated in 60% of primary high-grade/malignant gliomas and the extent of activation correlates positively with glioma grade." (PMID 20113523, 2010). "In summary, the combination of Src and STAT3 inhibition appears to achieve significant potentiation in diminishing both proliferation and migration in glioma cells." (PMID 20808823, 2010). "Taken together our studies suggest that (i) Iripallidal induces glioma cell apoptosis and (ii) inhibits Akt/mTOR and STAT3 pathway." (PMID 20576128, 2010). "We also assessed the functional role of c-Src and STAT3 in glioma cell migration by examining the effects of knockdown of Src, STAT3 or the combination of both by siRNA." (PMID 20808823, 2010). "Since Iripallidal inhibits mTOR and STAT3 activation in glioma cells we investigated its ability to regulate telomerase activity." (PMID 20576128, 2010). "As mTOR inhibitor blocks STAT activation and glial differentiation and since STAT3 inhibitors induce apoptosis in glioma cells, we determined the status of STAT3 activation in Iripallidal treated cells." (PMID 20576128, 2010). "The cytotoxic effects of combining Src and STAT3 inhibition on glioma cell lines were evaluated using assays to measure cell proliferation, apoptosis and migration." (PMID 20808823, 2010). "In this study, we found that a higher percentage of PBMCs expressed p-STAT-3 in glioma patients than in healthy donors." (PMID 19900287, 2009). "Moreover, SRPK1 directly regulates the Wnt/β-catenin and JAK2/STAT-3 signaling pathways, thus promoting glioma development." (PMID 41141389, 2026). "This raises the possibility that Calanquinone A may also interfere with the stemness properties of glioma cells through STAT3 inhibition." (PMID 40759869, 2025). "The analysis indicated that p-STAT3 was predominantly expressed in glioma tissues." (PMID 40265014, 2025). "Moreover, activation of the PAI-1/LRP1 axis, involved in mast cell recruitment in gliomas, enhances STAT3 phosphorylation and exocytosis." (PMID 40002669, 2025). "Additionally, DMAMCL has been shown to inhibit STAT3 phosphorylation by directly binding to STAT3, reducing PD-L1 expression in glioma cells, as phosphorylated STAT3 binds to the PD-L1 promoter to modulate its transcription." (PMID 40051564, 2025). "In addition, ACT001 can directly bind to IKKβ/STAT3 to induce apoptosis and inhibit the migration of glioma cells." (PMID 40468625, 2025). "This characteristic makes USP38 a promising candidate for targeted cancer therapy, as the USP38/JAK2/STAT3 signaling axis regulation may be specific to certain malignancies, such as glioma." (PMID 40936898, 2025). "Metformin may indirectly or directly affect the phosphorylation and nuclear translocation of STAT3 through the AMPK-mTOR pathway, thereby reducing its transcriptional activity and inhibiting the malignant phenotype associated with glioma stem cells." (PMID 39944825, 2025). "Notably, tissue microarray (TMA) and immunohistochemistry (IHC) analysis of phosphorylated STAT3 (p-STAT3) underscored the importance of STAT3 signaling in glioma." (PMID 40265014, 2025).
glioma (continued). "Importantly, SIRT6 overexpression inhibits the activation of the JAK2/STAT3 (Janus kinase 2/signal transducer and activator of transcription 3) signaling pathway, which is often overactive in gliomas, contributing to the anti-cancer effects of SIRT6." (PMID 40710366, 2025). "Furthermore, it suppresses human glioma cells (U87 and U251) by promoting STAT3 degradation through the ubiquitin-proteasome pathway." (PMID 40076568, 2025). "It is suggested that metformin may be a promising new strategy to regulate the effect of STAT3 on glioma stem cells and then treat glioma." (PMID 39944825, 2025). "Additionally, a systematic evaluation of specimens across different WHO grades showed that p-STAT3 expression was significantly higher in WHO grade IV gliomas compared to WHO grades II and III." (PMID 40265014, 2025). "Furthermore, IHC staining of tissue microarrays showed a significant association between p-STAT3 protein levels and the WHO grade of glioma, underscoring the significance of the STAT3 signaling pathway." (PMID 40265014, 2025). "Furthermore, the results of vivo experiments and IHC has confirmed the impact of F3-T3 on glioma malignant progression and activation of the STAT3 signaling pathway." (PMID 40265014, 2025). "Moreover, ZDHHC15 expression is significantly upregulated in glioma, promoting malignancy via the STAT3 signaling pathway, offering a novel prognostic biomarker for glioma patients." (PMID 40814339, 2025). "Additionally, the STAT3 (signal transducer and activator of transcription 3) signaling pathway, which is often highly active in glioma cells and contributes to drug resistance, was remarkably inhibited in Res/TMZ-treated GBM cells." (PMID 41009025, 2025). "A recent study also showed promising results with a combination drug containing an aptamer targeting PDGF beta and siRNA targeting STAT3, leading to reduced growth in both in vitro and in vivo glioma models, and utilized subcutaneous xenografts for in vivo experiments." (PMID 40427146, 2025). "Differential gene analysis and subsequent GSEA identified potential association of F3-T3 with various cancer-related pathways, including the interleukin 6-janus kinase-STAT3 (IL6-JAK-STAT3) pathway, indicating its role in the malignant progression of glioma cells." (PMID 40265014, 2025). "Based on the findings above, we hypothesized that STAT3 is a crucial mediator of the F3-T3-induced malignant progression in glioma." (PMID 40265014, 2025). "We further investigated whether STAT3 expression reversed the effects of Calanquinone A on glioma cell proliferation and migration." (PMID 40759869, 2025). "Dual CSF1R/PI3Kγ blockade simultaneously suppresses STAT3-driven signalling, decreases serum sCD163 pharmacodynamic biomarker levels, and is tolerated up to 800 mg daily with reversible transaminase elevation in phase-I glioma cohorts." (PMID 40995359, 2025). "Overall, these findings support the hypothesis that F3-T3 drives the malignant progression of glioma cells via the activation of STAT3 signaling pathway." (PMID 40265014, 2025). "JAK/STAT3 is a key signaling pathway regulating glioma pathogenesis and progression." (PMID 40321161, 2025). "Additionally, metformin affects glioma stem cells by inhibiting key pathways, including STAT3, mTOR, and AKT, and altering the tumor microenvironment." (PMID 39944825, 2025). "Similar to IL-33 and its downstream mediator IL-6, CD276 may have a role in the activation of STAT3 downstream signaling, which enhances stem-like characteristics in glioma cells and induces an anti-inflammatory phenotype in TAMs." (PMID 40136662, 2025). "Downregulation of miR-124 led to elevated levels of STAT3 in glioma cells." (PMID 39485747, 2024). "CYB561D2 up-regulation activates STAT3 to induce immunosuppression and aggression in gliomas." (PMID 37469162, 2024). "STAT3 is also a key driver of diffuse invasion and glioma growth, so STAT3 may be an effective target for controlling glioma invasiveness." (PMID 38495483, 2024).
glioma (continued). "Besides, we found the expression level of p‐STAT3 and STAT3 was also decreased, which were related to the cell proliferation in glioma." (PMID 39544152, 2024). "Therefore, resveratrol’s ability to inhibit JAK2 and STAT3 signaling pathways positions it as a potential therapeutic agent in gliomas, leading to reduced tumor growth and increased apoptosis." (PMID 39769099, 2024). "Furthermore, the main role of the cAMP/PKA pathway in the phosphorylation of STAT3 was also observed in glioma and macrophage cells." (PMID 39500352, 2024). "In glioma stem cells (GSCs), STAT3 activation leads to increased secretion of macrophage inhibitory cytokine-1 (MIC-1), IL-10, IL-4, and transforming growth factor β (TGF-β), which inhibit the phagocytic activity of macrophages and induce them to become immunosuppressive." (PMID 38254796, 2024). "The JAK2/STAT3 pathway is important in many cancers, especially gliomas." (PMID 38661644, 2024). "Thus, the present study was designed to investigate the expression of selected hypoxia related factors including STAT3 in a small set of long-term surviving glioma patients." (PMID 38654280, 2024). "Moreover, the findings indicate a statistically significant upregulation of STAT3 mRNA expression within high-grade gliomas compared to low-grade gliomas (P < 0.05)." (PMID 38238515, 2024). "Furthermore, the findings of western blot and immunochemistry assays demonstrated that up-regulation of miR-410 in glioma cells can inhibit STAT3 expression in vitro and in vivo." (PMID 38238515, 2024). "Additionally, H2O2 activated signal transducer and activator of transcription 3 (STAT3) in glioma cells." (PMID 37469162, 2024). "To further verify the hypothesis that the pro-tumorigenic activities are blunted in the SorLA-KO animals, we focused on the phosphorylation status of STAT3 in the glioma-bearing brains." (PMID 38499808, 2024). "Furthermore, ARSD serves as a prognostic biomarker that facilitates the progression of glioma cells via the activation of the JAK2/STAT3 signaling pathway and infiltration of M2 macrophages." (PMID 38895621, 2024). "Previous studies have confirmed that the activation of STAT3 is related to the poor prognosis of tumors, including head and neck tumors, B-cell lymphoma, cervical cancer, gastric cancer, colon cancer, liver cancer, glioma and esophageal cancer." (PMID 38710698, 2024). "Additionally, STAT3 inhibitors offer a promising approach to modulating glioma cell behavior by targeting the STAT3 signaling pathway." (PMID 39063221, 2024). "The growth and death of gliomas are closely related to STAT3." (PMID 39069522, 2024). "Notably, the pSTAT3-Y705/β-actin and pSTAT3-Y705/total STAT3 (except U-87) ratios exhibited higher values in Ctrl clones of glioma cell lines than in CSMD1-overexpressing clones." (PMID 38561856, 2024). "Our results further demonstrated that isocuB could impede glioma cell proliferation and migration by inhibiting STAT3 to inhibit MMP2/9." (PMID 38835342, 2024). "GLIPR1 could promote migration and invasion of glioma and epithelial-mesenchymal transition by mediating signal transducer and activator of transcription 3 (STAT3) pathway and IL-6." (PMID 38368374, 2024). "Blocking of the IL-6-mediated JAK2/STAT3 pathway could substantially suppress the proliferation and promote the apoptosis of glioma cells." (PMID 38715108, 2024). "In contrast, the STAT3 expression was elevated when endogenous miR-410 in glioma cells was reduced." (PMID 38238515, 2024). "Notably, Notch inhibitors, PI3K/AKT inhibitors, and STAT3 inhibitors emerge as frequent therapeutic targets, underscoring their pivotal roles in glioma pathogenesis and promising avenues for intervention." (PMID 39063221, 2024). "Furthermore, it has been observed to perform its function as a tumor suppressor in glioma cells through direct targeting of STAT3." (PMID 38238515, 2024).